JAK2 (Janus kinase 2)
Diseases named in the same sentence as JAK2 in open-access papers (continued):
Sharing a sentence is not in itself a finding about the gene and the disease.
cancer (continued). "Janus kinases (JaK) are a family of tyrosine kinases (TKs), including JAK1, JAK2, JAK3, and TYK2, and all of their receptors actively participate in the pathogenesis of various human cancers." (PMID 35634509, 2022). "The Janus kinase 2/signal transducer and activator of transcription 3 (JAK2/STAT3) pathway plays an important role in regulating cancer stem-cell properties of ATCs." (PMID 36430869, 2022). "Compared with normal ovaries and benign tumors, JAK2/STAT3 is activated in high-grade OC and is involved in cancer progression and EMT." (PMID 36591515, 2022). "Lee and colleagues (2018) further demonstrated that IL-35 secreted by mTAM triggers the JAK2/STAT6/GATA3 pathway in orthotopic tumor model mice, which encouraged the spread of cancer cells by reversing the epithelial–mesenchymal transition." (PMID 35682652, 2022). "It was found that MBZ inhibited S1P-induced cancer cell growth, and MBZ showed a growth inhibitory effect by regulating the JAK2/STAT3/Bcl-2 pathway." (PMID 36500220, 2022). "This study evaluated the cytotoxic and P-gp inhibitory activity of fedratinib, a recently FDA-approved JAK2 inhibitor, in P-gp-overexpressing MDR cancer cells." (PMID 35562984, 2022). "The treatment with azilsartan significantly (p < 0.001 and p < 0.01) decreased the expression of JAK2 protein in MCF-7 and MDA-MB-231 cancer cell lines, respectively, when compared to the untreated cells." (PMID 36431925, 2022). "As a result of examining the phosphorylation of JAK2 and STAT3, which are involved in the growth and death of cancer cells, phosphorylation was increased in the 5 μM S1P treatment group." (PMID 36500220, 2022). "JAK2/STAT3 signaling plays a crucial role in tumorigenesis—including cell proliferation and migration, radioresistance, and cancer cell stemness, and strategies targeting this pathway hold promise in anticancer drug development." (PMID 35269562, 2022). "Since we observed the anti-cancer activity of AZD1480 in SNU308 cells, we are planning to develop novel small chemical drugs from synthetic and FDA approved drug library to target JAK2." (PMID 35207737, 2022). "RNF6 promotes drug resistance through JAK2/STAT3 signaling pathway and RNF6 upregulation can render cells resistant to multiple anti-cancer drugs." (PMID 35369571, 2022). "JAK2/STAT3 has also been confirmed to be critically involved in the growth and metastasis of multiple cancers, including OCSS." (PMID 35513871, 2022). "SH2B3 bound to JAK2 and SHP2 to repress JAK2/STAT3 and SHP2/Grb2/PI3K/AKT signaling pathways, respectively, resulting in reduced cancer cell anoikis resistance, proliferation, migration, invasion, and EMT." (PMID 35589677, 2022). "Because GM-CSF induces PD-L1 expression in a JAK2/STAT5 dependent manner, treating cancers with dysregulated JAK/STAT5 signaling using GM-CSF would lead to disease progression." (PMID 35865534, 2022). "IL-6/JAK2/STAT3 signaling pathway plays a crucial role in the development and progression of cancer." (PMID 36591515, 2022). "The JAK2-modulated STAT3 transcription factors are involved in many processes, such as immune response, inflammation, and cancer progression, by activating proinflammatory cytokines, growth factors, and oncogenes." (PMID 35111269, 2022). "CuE can also suppress angiogenesis by inhibiting the VEGFR2-mediated JAK2 − STAT3 signalling pathway and cancer cell metastasis by inhibiting depolymerization of actin filaments." (PMID 35193614, 2022). "For JAK2/STAT3 signaling pathway, it was reported to plays vital roles in the EMT, metastasis and drug resistance of various cancers 28-29." (PMID 35813296, 2022). "In this study, we assessed the cytotoxic effects of JAK2 inhibitor, fedratinib, on drug-resistant KBV20C cancer cells." (PMID 35562984, 2022). "All of these findings together suggested that OPN promoted cancer growth, ROS production, NOX1 expression, and phosphorylation of JAK2/STAT3 in vivo." (PMID 35418176, 2022).
cancer (continued). "Janus kinase 2 (JAK2) and signal transducer and activator of transcription 3 (STAT3) signaling is an essential pathway in human cancers, as well as CSCs, acting by regulating inflammatory cytokines such as interleukin (IL)-6." (PMID 33805840, 2021). "In GSEA enrichment, cancer-related pathways, such as the TGF-β, MAPK, and JAK2 signaling pathways, were significantly identified." (PMID 33739392, 2021). "JAK2/STAT3 inhibition can dampen the polarization of M2-type macrophages and slow down the progression of cancer." (PMID 34604066, 2021). "The phosphorylation levels of MEK1/2, ERK1/2, JAK2, STAT3, PI3K, and Akt in cancer cells were detected by western blot." (PMID 34642304, 2021). "9p21.3 was the most significantly deleted segment in AK and harbors 10 cancer genes, including CDKN2A, JAK2, and MLLT3." (PMID 33482222, 2021). "Blockade of CAFs-LRG1 signaling cascade either by inhibitor or siRNA targeting JAK2/STAT3 axis can effectively attenuate migration and invasion of cancer cells induced by CAFs." (PMID 34930899, 2021). "circ-ZNF124 negates the miR-337-3p-mediated repression of JAK2/STAT3, and the consequent activation of this pathway increases cancer cell growth, migration, and colony formation abilities." (PMID 34205978, 2021). "Immunoblot analysis showed that the phosphorylation levels of JAK2 and STAT3 in cancer cells were down-regulated by matrine." (PMID 34642304, 2021). "Thanks to IL-6 autocrine and paracrine stimulus, CAFs upregulate VEGF, activate the JAK2/STAT3 pathway, express MCP-1, CCL11/8/20, CXCL5 and IL-9 for cancer cell invasion, growth and survival." (PMID 34944856, 2021). "In summary, we found that many human cancer cell lines fail to respond to STING agonists, which can be rescued by JAK2/STAT3 inhibitors in some cases." (PMID 33790360, 2021). "SNHG3 was previously found to exert oncogenic roles in a plethora of cancers: Based on current studies, SNHG3 was involved in TGF-β, NOTCH, JAK2/STAT3 and HGF pathway to promote cancer cell proliferation, invasion and inhibit apoptosis rate." (PMID 33596916, 2021). "The phosphorylation levels of MAPK/ERK, JAK2/STAT3, and PI3K/Akt signaling pathways in cancer cells were examined, respectively." (PMID 34642304, 2021). "Collectively, matrine targeted Src, inhibited its kinase activity, and down-regulated its downstream MAPK/ERK, JAK2/STAT3, and PI3K/Akt phosphorylation signaling pathways to inhibit the proliferation of cancer cells." (PMID 34642304, 2021). "Altogether, silibinin can inhibit cancer hallmarks against NSCLC cells and also inhibited PD-L1 expression through EGFR-mediated PI3K/AKT and JAK2/STAT5 signaling mechanisms." (PMID 34209829, 2021). "Previous reports have stated that the SOCS3/JAK2/STAT3 axis modulates the occurrence and development of various cancers." (PMID 34388111, 2021). "Matrine targeted Src, inhibited its kinase activity and tyrosine phosphorylation to inhibit the proliferation of cancer cells by down-regulating the downstream MAPK/ERK, JAK2/STAT3, and PI3K/Akt phosphorylation signaling pathways." (PMID 34642304, 2021). "Recent study showed that salidroside had anti-cancer effects and suppressed RCC proliferation through inhibition of JAK2/STAT3 signaling pathway." (PMID 33917914, 2021). "Meanwhile, matrine down-regulated the phosphorylation levels of MAPK/ERK, JAK2/STAT3, and PI3K/Akt signaling pathways by targeting Src in cancer cells." (PMID 34642304, 2021). "The results demonstrated that Src activator peptide increased and KX2-391 decreased the phosphorylation levels of MEK1/2, ERK1/2, JAK2, STAT3, PI3K, and Akt in cancer cells." (PMID 34642304, 2021).
cancer (continued). "IL-6 cooperates with TNF-α also in stimulating the Janus kinase (JAK)-signal transducer and activator of transcription (STAT), the JAK2/STAT3 pathway, which is involved in inflammation, cancer progression, muscle mass wasting, and cancer-related cachexia." (PMID 34684523, 2021). "The GSEA results also showed that metastasis samples were significantly enriched in several well-known cancer-related pathways, such as the TGF-β, MAPK, and JAK2 signaling pathways." (PMID 33739392, 2021). "The primary molecular targets of Zotiraciclib are CDK proteins, but Zotiraciclib has also been shown to inhibit Jak2 and FLT3 in cancer cells." (PMID 34680353, 2021). "GSEA results showed that the TCGA and GSE62229 samples were significantly enriched in several well-known cancer-related pathways, such as the TGF-β, MAPK, and JAK2 signaling pathways." (PMID 33739392, 2021). "JAK2, in the RTK-RAS pathway has also garnered significant interest in the past as a key driver of cancer cell survival, proliferation and invasion in GB." (PMID 33922652, 2021). "Downregulation of JAK2/STAT3/CCND2 signaling to sensitize cells to radiotherapy and impair cancer stemness." (PMID 32872659, 2020). "Increased expression of HSP90 activates oncogenic protein kinases JAK2/STAT3, PI3K/AKT and MAPK that facilitates cancer cell progression cancer." (PMID 33096691, 2020). "MiR-135a is dysregulated in various cancers and regulates cancer cell proliferation and invasion via several signaling pathways, such as the MAPK and JAK2/STAT3 pathways." (PMID 32944391, 2020). "Known cancer genes such as COL1A1 or STK11 were affected by duplications and other known genes such as CDKN2A, JAK2, PRDM1, FBXW7, or GOLGA5 were affected by deletions in several tumors of this subcluster." (PMID 32604718, 2020). "Activation of JAK2/STAT3 signaling in pancreatic cells appeared to be responsible for leptin-induced MMP13 over-expression and, as a consequence, for cancer invasion and metastasis." (PMID 32659999, 2020). "Growing studies have revealed that the inactivation of PTEN gene enhances the activation of PI3K/Akt and JAK2/STAT3 pathway, which in turn leads to the initiation, and malignant progression of cancers." (PMID 32626519, 2020). "and their active ingredients (e.g., cordycepin, salidroside, and gallic acid) have been reported to possess anticancer activity by targeting some apoptosis pathways in cancer, such as Bcl-2/Bax, caspases, PI3K/Akt, JAK2/STAT3, MAPK, and AMPK." (PMID 32774302, 2020). "JAK2/STAT3 pathway plays an important role in cell proliferation, differentiation and inhibition of apoptosis in number of cancers." (PMID 33123268, 2020). "A recent study suggested that the proteasome inhibitor YSY01A downregulates gp130 and the activation of JAK2 and STAT3 through a lysosome-autophagy pathway in cancer cells." (PMID 32581853, 2020). "To evaluate if IST5 affects kinase activity in cancer cells, we tested kinase inhibitory activity of IST5 in two custom-tailored panels including 54 relevant kinases, including Jak1, Jak2, Jak3, Tyk2, Abl1, Abl2, Lck, Fyn, Src and TrkB/C." (PMID 33217941, 2020). "The molecular mechanisms are mainly through targeting some apoptotic pathways in cancer, for example, Bcl-2/Bax, caspases, PI3K/Akt, JAK2/STAT3, MAPK, and AMPK." (PMID 32774302, 2020). "Several signaling pathways, including IL‐6/JAK2/STAT3 and TGF‐β/Smad, as well as the crosstalk between them, contributed to EMT and cancer stemness." (PMID 31860165, 2020). "Many studies have shown that inducing the inactivation of JAK2 can inhibit STAT3 activation and can thus inhibit STAT3 signaling, which then regulates apoptosis of cancer cells." (PMID 33330321, 2020). "Previously, we demonstrated that induction of EMT programs by TrkB results in cancer acquiring metastatic potential by suppressing the SOCS3-mediated degradation of JAK2 that subsequently activates the PI3K/AKT and IL6/JAK2/STAT3 signaling pathways." (PMID 32340410, 2020).
cancer (continued). "The pathways activated in cancer processes by α7-nAChR activation-nicotine mediated are generally Ras/ERK/MAPK and JAK2/STAT/-PI3K pathways, leading to cancer cell proliferation and migration as demonstrated in lung cancer cells." (PMID 33120929, 2020). "Alone this line, our finding added another path, ARL4C/JAK2/STAT5/β-catenin, as a new means for cancer cells to escape the survival inhibition by Erlotinib." (PMID 33194732, 2020). "The IL-6/JAK2/STAT3 pathway was discovered to be constitutively activated in human CRC and significantly related to cancer cell proliferation, invasion, and migration." (PMID 32518521, 2020). "Intriguingly, it has been elucidated that STAT3 can be activated by IL-6 through Janus kinase 2 (JAK2), and IL-6/JAK2/STAT3 has been implied as a crucial accelerator for tumorigenesis and EMT in many cancer types, including HCC22." (PMID 31949128, 2020). "We first classified these variants for which sufficient evidence exists that the corresponding amino acid change is a driver in cancer (e.g., EGFR p.(Leu858Arg) or JAK2 p.(Val617Phe))." (PMID 31888289, 2019). "ADAR1 expression is positively regulated by JAK2 signaling, and is overexpressed in CML and presumably in other cancers where JAK2 signaling is increased." (PMID 31468250, 2019). "Effects of apigenin on JAK2/STAT3 pathway and cytotoxicity in cancer cells were mediated by its docking to 26S proteasome in cancer cells." (PMID 31100782, 2019). "IL-6, JAK1, JAK2 and STAT3 which are considered main components of this pathway, have been found to be overexpressed in different cancers, including BCC." (PMID 31342143, 2019). "In line with an important role of EGFR and IL6 signaling in GLI-driven cancers, genetic and pharmacological inhibition of EGFR and IL6/JAK2/STAT3 signaling, respectively, interferes with GLI-driven tumor growth." (PMID 30991683, 2019). "The JAK2/STAT3 signaling mediates the effects of many growth factors and cytokines, and has been intensely investigated in many cancer types." (PMID 30782177, 2019). "In this study, we found that JAK2/STAT3 signaling was preferentially enriched in the CSC population and required for their cancer-repopulating capacity." (PMID 31511084, 2019). "A panel of eight cancer driver genes (CCNE1, TPX2, ELF3, FANCL, JAK2, GSK3B, CEP76, and SYK) were differentially expressed in recurrent TNBCs, and were also overexpressed in TCGA and METABRIC." (PMID 30665374, 2019). "Crosstalk of gas signaling molecules with other signaling pathways such as JUN, JAK2, JAK3, and NF-κB, upregulates p38MAPK, hypoxia, immune cell, and cancer metastasis signaling." (PMID 30972102, 2019). "Thus, JAK2/STAT3 could serve as a potential target for cancer therapy." (PMID 31540495, 2019). "The JAK2-modulated transcription factor STAT3, involved in immune responses, inflammatory processes, and cancer initiation, is activated by several cytokines, growth factors, and oncogenes." (PMID 31492006, 2019). "2-Methoxystypandrone was able to block STAT3 and NF-κB pathways by covalently interacting the upstream kinase JAK2 and IKK, inhibited cell growth/survival, and eventually induced apoptosis in human cancer cells." (PMID 30709346, 2019). "We found that JAK2 and STAT3 were reduced after LDR treatment in both 850-5C and BCPAP cancer cells." (PMID 30760304, 2019). "Next, to evaluate the therapeutic effects of JAK2 depletion on CSCs in vivo, we isolated cancer cells from the primary tumors of CRC xenograft mice and analyzed their cancer-repopulating efficiency by the LDA." (PMID 31511084, 2019). "Further JAK2 phosphorylation also correlates with both STAT3 and STAT5 phosphorylation, suggesting that the JAK2/STAT3 and JAK2/STAT5 pathways are functional in these cancer cells." (PMID 31817106, 2019). "In an ovarian cancer cell line pY-STAT3 co-localizes with TYK2 and JAK2 at focal adhesions, and hyperactive STAT3 was shown to promote cancer cell motility." (PMID 31694222, 2019).
cancer (continued). "Momelotinib, an inhibitor of JAK1/JAK2, consistently abrogated the STAT5/LY6G6D axis in vitro, sensitizing MSS cancer cells with an intact JAK-STAT signaling, to efficiently respond to trametinib, a MEK inhibitor used in clinical setting." (PMID 30670049, 2019). "In cancer cells, oncogenic tyrosine kinases (BCR-ABL, JAK2) are highly expressed and perform tyrosine phosphorylation of pyruvate dehydrogenase kinase 1 (PDHK1)." (PMID 31847192, 2019). "The IL6, phosphorylated JAK2, phosphorylated STAT3 and SOX2 protein levels in 97L cancer cells were greatly elevated by SHH treatment." (PMID 29722127, 2018). "Since persistent activation of STAT3 is oncogenic and is prevalent in a wide variety of human cancers, such as CRC, we focused on the JAK2/STAT3 pathway." (PMID 30564118, 2018). "Mechanically, resveratrol treatment decreased cytokines synthesis and inhibited JAK2/STAT3 signaling, which was consistent with the decline of cancer stem cells marker, CD133." (PMID 30356255, 2018). "We documented that IL-6 secreted by IR cells activates the JAK2 and STAT3 pathway through IL-6 receptor in cancer cells, leading to the IGF-1Ec upregulation and PEc secretion, as well as to the IL-6 expression and secretion." (PMID 30134795, 2018). "JAK2 is the major kinase of STAT3 and has been reported to be constitutively active in many cancers and other proliferative diseases." (PMID 29921758, 2018). "Novel therapies are desperately needed, and this has led to investigation of the JAK2/STAT3 pathways, which appear to be play an important role in carcinogenesis of numerous cancers." (PMID 29986501, 2018). "Since PN is a JAK2 covalent inhibitor and can inhibit the IL-6-induced STAT3 activation, we next examined the effect of PN on the IL-6-induced cancer cell migration." (PMID 29921758, 2018). "Compounds identified from AC have been reported to inhibit the phosphorylation of JAK2 and STAT3 in cancer cells." (PMID 30618745, 2018). "Activated forms of JAK2 and STAT5 have been reported in human early breast lesions and cancer and in other human cancers." (PMID 29778097, 2018). "One of the most important common pathways mediating resistance is JAK2/STAT5 signaling pathway activation, promoting cancer stem cell survival and self-renewal." (PMID 29472718, 2018). "Both Src and JAK2 are the upstream tyrosine kinases of STAT3, and they have been found to be constitutively phosphorylated/activated in various cancers including CRC." (PMID 28503147, 2017). "It is reported that activated EPOR signals through JAK2 and downstream STAT5, PI3K/AKT or RAS/RAF/ERK to promote pro-proliferative or anti-apoptotic cancer cell growth." (PMID 29137269, 2017). "This process has been reported to induce JAK2/STAT3 phosphorylation and can contribute to cancer cell survival." (PMID 28894215, 2017). "One mechanism by which cancer cells could escape the effects of IFN-γ is by decreasing the expression or mutations in molecules in IFN-γ signaling pathway, which goes through the IFN-γ receptors JAK1 and/or JAK2 and the signal transducer and activators of transcription (STATs)." (PMID 29299180, 2017). "Next, we questioned how TM4SF4 activates the JAK2/STAT3 pathway or SRC/FAK/STAT3 pathway, which also reinforces EMT or CSC-like properties of cancer cells." (PMID 29254164, 2017). "Further, JAK2/STAT3 signaling pathway is involved in the sustaining of self-renewal and tumorigenicity, which is constitutively phosphorylated in cancer cells." (PMID 29348843, 2017). "Leptin is known to activate a number of different signaling pathways, particularly the JAK2/STAT3 pathway, including in cancer cells." (PMID 29212170, 2017). "Several small molecule inhibitors targeting DNA methyltransferases (DNMTs), histone deacetylases (HDACs) and janus kinase 2 (JAK2) have already been granted approval by the US Food and Drug Administration (FDA) for the treatment of certain cancers." (PMID 28029659, 2017).